TSLP (thymic stromal lymphopoietin)
Diseases named in the same sentence as TSLP in open-access papers (continued):
Sharing a sentence is not in itself a finding about the gene and the disease.
cancer (continued). "It is important to emphasize that the differential expression and the functions of the two TSLP isoforms in human and experimental cancers are presently unknown." (PMID 34440780, 2021). "Further studies on the roles of TSLP isoforms and their localization in peritumoral and intratumoral areas of tumors could help clarify the TSLP role in different cancers." (PMID 34440780, 2021). "Two variants of TSLP, long-form (lfTSLP) and short-form (sfTSLP), have been found, however their roles in cancers are not known." (PMID 33652749, 2021). "The release of angiogenic and lymphangiogenic mediators from TSLP-activated macrophages might explain, at least in part, the protumorigenic role in TSLP in several human cancers." (PMID 34440780, 2021). "Here, we focus exclusively on the literature regarding TSLP expression and function in cancer with special emphasis on the association or not with Th2 inflammation." (PMID 33042121, 2020). "Concurrent with these previous reports, our results revealed significant univariate associations of TSLP overexpression with FIGO grade, histological differentiation, pelvic involvement, and lymph node involvement in EOC; thus, indicating aggravated cancer growth, progression, and metastasis." (PMID 31023965, 2019). "More evidence has reported an essential role of TSLP in the development of allergic disorders, including atopic dermatitis and allergic bronchial asthma (Sebastian, Borowski, Kuepper, & Friedrich, 2008; Ziegler, 2010) as well as genesis of malignant tumors." (PMID 31210014, 2019). "In addition, these results suggest the pathological role of TSLP in the development of other malignant carcinomas, as well as the poor prognosis of patients with TSLP overexpression." (PMID 31023965, 2019). "Since TSLP overexpression could drive the development of Th2-dominant carcinomas, our results here suggest that TSLP may also play an important role in growth, invasion, and progression of EOC, possibly through manipulation of the immune response." (PMID 31023965, 2019). "Finally, studies are urgently needed to examine the differential expression and functions of sf TSLP and lf TSLP on patients with cancer." (PMID 30057581, 2018). "However, the role of TSLP in cancer appears increasingly controversial, even paradoxical, as it exerts either pro- or anti-tumorigenic effects, depending on the context." (PMID 30214685, 2018). "Thymic stromal lymphopoietin can inhibit colon cancer by inducing apoptosis of cancer cells." (PMID 28032353, 2017). "Thus, down-regulation of STAT3 phosphorylation strongly supported our findings that TSLP promoted the apoptosis of cancer cells." (PMID 26919238, 2016). "TSLP recently has emerged as a contributing factor to some cancers." (PMID 26919238, 2016). "It is that high expression level of TSLP in cancer increases the Th2 level." (PMID 25075970, 2014). "In addition, more evidence are emerging implicating TSLP involvement in different types of cancers." (PMID 39726595, 2024). "However, the possible TSLP regulatory mechanisms underlying these cancers are not clear and varied in different tumors." (PMID 34573368, 2021). "TSLP inhibition could be an important key for the future of BC cancer therapy." (PMID 31210014, 2019). "However, it appears likely that local quantitative and/or qualitative perturbations in the TSLP isoform or TSLP receptor expression may be an initiating and/or driving force, contributing to cancer formation and progression." (PMID 30214685, 2018). "TSLP limits primary and recall responses of CD8+ T cell, which play a critical role in cancer immunity." (PMID 40873585, 2025). "Thymic stromal lymphopoietin (TSLP), a cytokine primarily generated by activated epithelial cells, has recently garnered attention in cancer research." (PMID 38557942, 2024).
cancer (continued). "Top up-regulated genes related to cancer were: (i) IL-20, CLK1, SORBS2, ERG1, PIM1, SNORD3A for normal FHC cells and (ii) TSLP, BHLHA15, LAMP3, ZNF27B, KRT17, ATF3 for cancerous HT29 cells." (PMID 38033043, 2023). "First, cancer cells and TAMs produce TNFα and IL1-β, which activate CAFs to produce thymic stromal lymphopoietin (TSLP)." (PMID 35205732, 2022). "Collectively, these results showcase the antitumor function of TSLP and CD4+ T cells, which can be a promising therapeutic strategy for cancer immunoprevention and treatment." (PMID 36467403, 2022). "We also found that TSLP from cancers prepares the metastasis “soil”, such as inducing expression of CCL17 in the lungs to recruit CCR4+ cancer cells and their protector CCR4+FoxP3+ Tregs and Th2-skewed CD4+ T cells." (PMID 36104343, 2022). "Immune-suppressive cytokines such as TSLP (thymic stromal lymphopoietin), TGFβ, IL-10, and INOS were often found to be elevated in HH-hyperactivated cancers." (PMID 34831357, 2021). "The relevance of TSLP-dependent TH2 inflammation in allergic disorders and in cancer has been recently emphasized." (PMID 34440780, 2021). "It has been reported that human cervical carcinoma cells release TSLP acting on TSLPR+ endothelial cells to promote angiogenesis and cancer growth." (PMID 30057581, 2018). "Actually, similar to TSLP, another important protein TRAIL also preferentially induced apoptosis in cancer cells." (PMID 26919238, 2016). "In contrast, advanced cancer cells are no longer capable of initiating a differentiation program and they respond to TSLP-activated CD4+ T cell immunity by undergoing senescence." (PMID 36467403, 2022). "The results showed that high expression of TSLP, RASGRP1, APOD, and PTGER3 was correlated with cancer cell drug sensitivity to a variety of chemotherapeutic drugs, especially APOD, which was highly correlated with drug sensitivity to ARQ-680, SB-590885, PLX-4720, vemurafenib, and others." (PMID 36467500, 2022). "Two main isoforms of TSLP, classified as long- (lfTSLP) and short-form (sfTSLP), have been reported in human, but their expression patterns and role(s) in cancers are not yet clear." (PMID 33652749, 2021). "We also detected differentially methylated regions in cancer-related genes, such as CMYA5, TSLP, ZNF503, and ZNF217, which suggest that the methylation status of these genes may be involved in tumorigenesis or cancer progression." (PMID 34527193, 2021). "It was also found that calcipotriol did not have this cancer-protective effect in animal models lacking the TSLP receptor, thus clearly demonstrating the importance of TSLP in mediating this cancer immunity effect of vitamin D analogs." (PMID 34306760, 2021). "In conclusion, the role of TSLP–TSLPR axis in experimental and human cancer is still controversial." (PMID 30057581, 2018). "It is obvious that there are many important questions that should be urgently addressed before we understand whether TSLP isoforms and TSLPR+ immune cells are an ally or an adversary in different types of human cancer." (PMID 30057581, 2018). "We found that the proliferation of cancer cells at 48 h was not affected by adding TSLP at all concentrations investigated as determined by BrdU Cell Proliferation Assay Kit." (PMID 26919238, 2016). "Hence, it is not surprising that TSLP would have a significant direct or indirect role in the regulation of experimental and human cancers." (PMID 40873585, 2025). "Although IFN-III and TSLP are both produced by epithelial cells and exert effects on antiviral and antitumor immune regulation, a direct or well-defined interaction between the two in moderating cancer or hypersensitivity disorder is still lacking." (PMID 37809098, 2023). "Therefore, it is not surprising that TSLP plays a direct and/or indirect role in the control of a variety of experimental and human cancers." (PMID 30057581, 2018).
cancer (continued). "Thus, given such emerging evidence of the involvement of TSLP in the abrogation of Th1, Th9, and Th17 inflammatory responses and its influence on a range of immune cell lineages it does not come as a surprise that TSLP is becoming more intensively studied in the context of cancer." (PMID 32849527, 2020). "Although TSLP-stimulated CD4+ Th2 cells are not cytotoxic themselves, they recruit a broad repertoire of immune effector cells to attack the cancer more effectively." (PMID 39782693, 2025). "Unexpectedly, there were no statistically-significant correlations between TSLP IRS and either inflammatory infiltrate or cancer cell OX40L IRS (Spearman correlation test: r = 0.133, p = 0.434; and r = –0.150, p = 0.372, respectively)." (PMID 30214685, 2018).
inflammation (43 papers, 2011 to 2025). Aberrant reaction of the microcirculation characterized by movement of fluid and leukocytes from the blood into extravascular tissues. "The association of high TSLP levels with IL-5 is in agreement with extensive evidence linking TSLP with eosinophilic airway inflammation." (PMID 36245744, 2022). "Since long-term exposure of mice to HDM, but not OVA, results in chronic airway inflammation associated with tissue remodeling, these observations suggest that IL-25, IL-33 and TSLP play different pathogenic roles in the acute and chronic phases of airway inflammation." (PMID 24205109, 2013). "Mice overexpressing TSLP exhibited an increase in the number of basophils that was directly related with systemic production of Th2 cytokines and the development of Th2 cytokine-associated intestinal inflammation." (PMID 23437132, 2013). "To clarify how basophil was activated in OVA-induced lung inflammation, we further analyzed the role of TSLP in the mouse model." (PMID 40443683, 2025). "Later, TSLP was identified as a key molecule in hMPV-induced lung inflammation, conducted through the genetic ablation and immunological blocking of the TSLP-TSLR pathway in hMPV-infected mice." (PMID 41471232, 2025). "Livin facilities nasal chronic inflammation by promoting the thymic stromal lymphopoietin (TSLP) expression in nasal epithelial cells." (PMID 35717553, 2022). "In various models of airway inflammation in mice, IL-33, IL-25 and/or TSLP showed increased expression in the lungs after inhalation of antigens." (PMID 33723298, 2021). "Recent studies have highlighted an important role of epithelial cytokines, including IL-25, IL-33 and TSLP, in lung inflammation." (PMID 34970267, 2021). "Together, these data suggest that TSLP-TSLPR signaling induces Bcl-xL up-regulation, which reduces cell apoptosis and bleomycin-induced airway inflammation caused by increased caspase-1 and caspase-3 activity in this setting." (PMID 32103153, 2020). "A similar phenotype was observed with the administration of anti-TSLP antibodies to C57BL/6 mice confirming that TSLP-TSLPR ligation confers protection in a model of damage-induced airway inflammation." (PMID 32103153, 2020). "We further investigated the role of TSLP in mouse models of airway inflammation through intranasal instillation of TSLP antibodies and phosphate buffer saline (PBS) as a control." (PMID 30184256, 2018). "We tested the hypothesis that pulmonary TSLP levels in asthmatic children correlate with clinical severity, airway inflammation and lower airway obstruction." (PMID 36245744, 2022). "Phenotypic analysis of ILC2s in this study showed upregulation of TSLPR on IL-33 receptor-expressing ILC2s, suggesting that increased responsiveness of ILC2s to TSLP in the airways may contribute to the spread of eosinophilic inflammation." (PMID 35572064, 2022). "Airway epithelial cells are the first line of defense against environmental allergens and secrete IL-33, IL-25, and thymic stromal lymphopoietin (TSLP) that can induce Th2 cells and type 2 innate lymphoid cell (ILC2) activation to potentiate allergen-induced Th2-associated airway inflammation." (PMID 34101619, 2021). "Human TSLP was first described to activate myeloid dendritic cells, which prime naïve T helper cells to produce high concentrations of Th2 cytokines, thus representing a key cytokine in triggering dendritic cells-mediated allergic Th2 inflammation." (PMID 33042121, 2020). "The effect of TSLP on murine type 2 airway inflammation might be variable depending on the type of allergens, time course, and tissues." (PMID 32066836, 2020). "TLR2 expression increased thymic stromal lymphopoietin (TSLP) production through the NF‐κB and JNK signaling pathways to extend the survival of recruited basophils and resident DCs in the lung, predisposing a type‐2‐cell‐mediated airway inflammation." (PMID 30184256, 2018).
inflammation (continued). "Herein, we hypothesize that in addition to mediate allergic airway inflammation and remodeling, epithelium‐derived triple cytokines, IL‐25/IL‐33/TSLP, can also potentiate non‐atopic lung parenchymal inflammation and fibrogenesis mainly by initiating and propagating type 2 immunity." (PMID 36082495, 2022). "This study aims to investigate the role of basophils in inducing lung inflammation through intranasal sensitization by OVA, in the presence of AD-like skin lesions in mice, and to explore the potential role of TSLP in activating basophils." (PMID 40443683, 2025). "Since the mechanism of action of papain in lung inflammation seems to be like that of MC903 in the skin, we decided to check the effect of DMOG on the TSLP expression using BEAS-2B bronchial epithelial cell lines." (PMID 36983043, 2023). "Activation of the EGFR pathway promotes Th2-type immune responses and TSLP release through the MEK/ERK and p38 MAPK signaling cascades, while the MAPK family (especially the p38 subtype) plays a key regulatory role in allergen-induced airway inflammation." (PMID 40605076, 2025). "Administration of human apoA-I to allergen-challenged wild-type mice similarly, suppressed airway inflammation, AHR, dendritic cell migration to the lung, and reduced the release of IL-25, IL-33, and TSLP (thymic stromal lymphopoietin) by airway epithelial cells." (PMID 27708582, 2016). "In conclusion, we demonstrated 2 distinct roles for the long and short TSLP isoforms; lfTSLP contributes to HDM-induced airway epithelial dysfunction, whereas synthetic sfTSLP exerts protective effects in HDM-induced airway inflammation and in the asthmatic mouse model." (PMID 27996052, 2016). "This epithelial injury triggers the release of alarmins IL-33 and TSLP, activates innate lymphoid cell types 2 (ILC2) and T cells, and promotes IL-5/IL-13-driven eosinophilic and interleukin-17A-mediated neutrophilic inflammation—resulting in mixed airway inflammation." (PMID 41450494, 2025). "Therefore, co-stimulation with TWEAK and TGF-β1 can induce the steroid-insensitive production of TSLP and CCL5 in the bronchial epithelium and may contribute to airway inflammation." (PMID 39519176, 2024). "However, IL-33, but not IL-25 or TSLP, was shown to be responsible for development of airway inflammation in mice sensitized “intranasally” with house dust mite antigens." (PMID 26230091, 2015). "Besides, the correlations between BIRC3 expression and asthmatic eosinophilic/allergic inflammation indicators (FeNO, IgE, and EOS%), pulmonary function (FEV1, FEV1% pred, FVC% pred, and FEV1/FVC), and inflammatory cytokines (IL-4, IL-5, IL-13, IL-25, IL-10, IL-33, and TSLP) were analyzed." (PMID 35287655, 2022). "However, we did not observe a significant reduction in lymphocyte numbers in the BALF from Tslpr−/− mice when compared with Tslpr+/+ mice suggesting that the effects of TSLP on the lymphoid compartment do not contribute to protection from bleomycin-induced airway inflammation." (PMID 32103153, 2020). "In addition, as demonstrated by two different types of murine type 2 airway inflammation models, we cannot entirely rule out the possibility that TSLP plays a role in promoting type 2 inflammation via different immune cell cascades in the context of other stimuli and/or tissues." (PMID 32066836, 2020). "On the other hand, only IL-33, but not IL-25 or TSLP, was important for induction of HDM-induced airway inflammation in mice sensitized “intranasally” with HDM35,36." (PMID 30082755, 2018). "On the other hand, IL-33, but not IL-25 or TSLP, was found to be important for development of HDM-induced “chronic” airway inflammation in mice." (PMID 24205109, 2013).
immune disorders (6 papers, 2012 to 2024). "TSLP is a pleiotropic cytokine that has been implicated in a variety of immune disorders, including different solid and hematologic tumors." (PMID 34440780, 2021). "TSLP is considered a pivotal cytokine linking innate and adaptive immune disorders." (PMID 24167583, 2013). "TSLP, a keratinocyte-derived triad of cytokines, has been studied intensively recently in the pathogenesis of allergic inflammation and subsequent development of AD and other immune disorder." (PMID 23284675, 2012). "TSLP stimulates dendritic cells (DCs) to induce naïve CD4+ T cell differentiation into TH2 cells and cytokine production, indicating that TSLP plays an important role in allergic and immune disorders." (PMID 31768185, 2019).
respiratory diseases (6 papers, 2019 to 2024). "Furthermore, the level of eotaxin-3 was found to be closely related to IL-33 and TSLP levels which indicate respiratory diseases." (PMID 30778348, 2019).
bacterial infection (2 papers, 2019 to 2022). "IL-25, IL-33, and thymic stromal lymphopoietin (TSLP) are mediators released by bronchial epithelial cells following viral, fungal, and bacterial infections." (PMID 35269941, 2022).
lung (2 papers, 2021 to 2022). "Our results put forward TSLP induction as a potential therapeutic approach that can trigger a lasting antitumor immune response capable of bringing the adaptive immune cells to recognize and suppress early stages of lung carcinogenesis." (PMID 35565302, 2022).
gynaecological diseases (1 paper, 2021). "Whilst the expression and effects of TSLP in gynaecological diseases have been investigated and reviewed, none of these studies have reported specifically on each TSLP isoform but collectively designated the isoforms as “TSLP”." (PMID 33652749, 2021).
hematological malignancies (1 paper, 2010). "Thus it will be interesting in future studies to correlate patient TSLP serum levels with the risk of developing hematological malignancies." (PMID 20174635, 2010). "The nature of the hematological disorder is dependent on the age of the mice (embryonic versus adult) while the development of the MPD appears to depend on the TSLP concentration." (PMID 20174635, 2010).
neurological diseases (1 paper, 2022). "The expression of TSLP is different in variable neurological diseases." (PMID 36287299, 2022).
renal diseases (1 paper, 2021). "Both, stem cell factor (SCF) and thymic stromal lymphopoietin (TSLP), are linked to the pathogenesis of renal diseases." (PMID 34205404, 2021).
vasculopathy (1 paper, 2021). "Also, serum TSLP was increased in SSc patients and associated with vascular dysfunction, indicating a possible earlier involvement of TSLP since vasculopathy occurs early in the progression of SSc." (PMID 34249003, 2021).
TSLP also shares sentences with these, for which no sentence is quoted: Allergy (82 papers); idiopathic pulmonary fibrosis (6); chronic rhinosinusitis with nasal polyps (3); eczema herpeticum (3); urticaria (3); B cell lymphoma (2); bronchiectasis (2); bullous pemphigoid (2); cardiovascular diseases (2); cystic fibrosis (2); hepatocellular carcinoma (2); Hodgkin disease (2); lymphoma (2); Multiple Organ Failure (2); myeloma (2); prostate carcinoma (2); skin infection (2); type 2 diabetes (2); abdominal aortic aneurysm (1); acute appendicitis (1); acute graft versus host disease (1); acute respiratory distress syndrome (1); adenocarcinoma (1); adenoma (1); Adenovirus infection (1); Behçet’s disease (1); blood cancers (1); breast invasive carcinoma (1); cartilage disease (1); Childhood onset (1).
A further 68 diseases each share a sentence with TSLP in 1 paper.